MMP9 (matrix metallopeptidase 9)
Diseases named in the same sentence as MMP9 in open-access papers (continued):
Sharing a sentence is not in itself a finding about the gene and the disease.
diabetes (continued). "MMP‐9 induced increase in expression of FasL in diabetes wound repair." (PMID 35657334, 2022). "In addition to diabetes treatments, MMP-9 and MMP-14 inhibitors can be used to slow down the progression of diabetic retinopathy and to prevent retinal damage." (PMID 35729613, 2022). "MMP9 is not only a biomarker of cancer cell invasion and tumor metastasis and expressed in various cancer cells, but also participates in the development of cardiovascular disease, lung disease, and diabetes." (PMID 35754483, 2022). "Binary logistic regression analysis was performed to determine the risk factors of the presence of diabetes and the effect of MMP-9 and MMP-14 levels on being diabetic/nondiabetic group." (PMID 35729613, 2022). "In summary, hybrid hydrogel dressings may constitute biocompatible materials that effectively promote the treatment of diabetes by effectively silencing the MMP-9 gene, providing a platform for siRNA applications in other diseases." (PMID 35745954, 2022). "In addition, we were interested in the level of MMP-3 and MMP-9 in patients with DM2 with EBV infection with different durations of diabetes and body mass index (BMI)." (PMID 36362386, 2022). "This is unlike previous studies showing MMP-9 is associated with arterial stiffness in patients with diabetes." (PMID 33579197, 2021). "However, another study has shown that MMP2 was elevated while MMP9 was decreased in the heart of diabetes rat." (PMID 34621323, 2021). "However, in pathological states involving inflammation, particularly in the setting of diabetes, MMP-9 is highly expressed and plays a central role in the turnover of ECM components such as collagen, proteoglycans and elastin." (PMID 33579197, 2021). "Age, diabetes, IL-6 and MMP-9 were significantly associated with a stiffness of ≥7.2 kPa in the multivariate model that included both demographic factors and serum-based markers (ghrelin, IL-6, TNFα and MMP-9)." (PMID 34813621, 2021). "The subgroup of MMPs known as gelatinases, in particular gelatinase A (MMP-2) and gelatinase B (MMP-9), can degrade COL and denatured COL (gelatin), and their altered activity might be implicated in the pathophysiology of diabetes complications." (PMID 34069322, 2021). "Yet, the expression of MMP-9 on renal tubular epithelial cells in diabetes mellitus remains unclear." (PMID 34082748, 2021). "This study builds on a growing body of evidence that MMP-9 may contribute to cardiovascular disease in people with diabetes." (PMID 33579197, 2021). "In this study, we found that MMP8 and MMP9 were upregulated in the knee joints of diabetic OA rats." (PMID 33468174, 2021). "In this regard, some authors suggest that MMP-2 may be a good index of the severity of microangiopathy, and MMP-9 may be a marker of macroangiopathy in diabetes." (PMID 34069322, 2021). "In diabetes, while retinal MMP-9 expression is upregulated, that of Timp1 is downregulated." (PMID 32150828, 2020). "In addition, MMP9 has been found to be involved in the pathogenesis of diabetes and diabetic complications, such as diabetic retinopathy." (PMID 32342229, 2020). "Additionally, HB liniment enhanced TGF-β1 and reduced MMP9 level, accelerating wound healing in diabetes." (PMID 32566084, 2020). "Based on these results, the authors postulated that MMP-2 may be a good index of the severity and stability of microangiopathy, and MMP-9 is a marker of macroangiopathy in diabetes." (PMID 32403389, 2020). "Study also suggested that MMP9 might connect with autophagy mediated contractile dysfunction in diabetes." (PMID 33292335, 2020). "For instance, in patients with diabetes, relevant alterations in circulating Tenascin-C, MMP-9, ET-1 or NGAL could be observed." (PMID 32545310, 2020). "Therefore, we are now investigating changes in IDE and MMP-9 in the lens epithelium of diabetic patients, and will attempt to demonstrate the relationship between diabetes-related factors and Aβ production and accumulation in the lenses of STZ rats." (PMID 32294928, 2020).
diabetes (continued). "Thus, hyperhomocysteinemia in diabetes activates MMP-9 functionally by reducing Timp1-MMP-9 interactions and transcriptionally by altering DNA methylation-hydroxymethylation of its promoter." (PMID 32150828, 2020). "Moreover, DHI inhibits CRISPR-associated gene 3, MMP2, and MMP9 expression and the formation of acellular capillaries in retinas; thus, DHI can prevent diabetes-induced apoptosis and protect retinas against diabetes-induced damage." (PMID 31892939, 2019). "However, ergosterol treatment efficiently reversed the reduction of MMP-2 and MMP-9 in diabetic kidneys." (PMID 30823598, 2019). "Furthermore, in inflammatory diseases such as arthritis, cardiovascular disease, cancer, and diabetes, MMP9 stimulates the immune response initiating pathogenesis and increasing disease progression." (PMID 30544510, 2018). "Furthermore, they presented three multivariate prediction models of mortality that include TIMP1/MMP9 ratio, diabetes and SOFA score measured at the first, fourth and eighth day." (PMID 28192449, 2017). "The results show that the recruitment of Ezh2 is increased at the MMP-9 promoter in diabetes." (PMID 29261844, 2017). "The results indicate that the impact of diabetes on MMP9 is FOXO1 dependent." (PMID 28874756, 2017). "In summary, using experimental models of diabetic retinopathy, and confirming results in the retinal microvessels from human donors with diabetic retinopathy, this study provides strong evidence of a crosstalk between histone and DNA modifications in the regulation of MMP-9 expression in diabetes." (PMID 29261844, 2017). "Diabetes in vivo or high glucose in vitro increased MMP9 expression by keratinocytes." (PMID 28874756, 2017). "As with HRECs, diabetes increased H3K27me3 levels at the MMP-9 promoter by approximately 4-fold, and this was accompanied by an increase in Ezh2 recruitment at the same site of the promoter; accompanying gel picture represents the band intensity on a 2% agarose gel." (PMID 29261844, 2017). "Thus, a close crosstalk between H3K27 trimethylation and DNA methylation in diabetes plays a critical role in the maintenance of cellular epigenetic integrity of MMP-9." (PMID 29261844, 2017). "15,16 Ezh2 expression is increased in retinal endothelial cells in diabetes, but, its role in regulating MMP-9 expression remains unclear." (PMID 29261844, 2017). "The increased MMP-1, MMP-2, and MMP-9 activities and expression induced by high glucose exposure can elevate matrix degradation thereby accelerating atherogenesis and potentially decreasing plaque stability in diabetes." (PMID 27781209, 2016). "Overexpression of MMP-2 and MMP-9 in diabetic atherosclerotic plaques may increase their vulnerability which, in turn, increases the risk of ischemic cardiovascular events." (PMID 27490532, 2016). "Moreover, we observed that the induction of retinal CAS-3, TNF-α, MMP-2, and MMP-9 expressions by diabetes was inhibited by NXT treatment, suggesting an antiapoptotic and anti-inflammatory effects of NXT." (PMID 25821481, 2015). "Therefore, this study explaining that exercise releases exosomes that contain microRNA to silence MMP9 can bridge a major gap between exercise, exosome mediated beneficial effects to heart and diabetes." (PMID 25824442, 2015). "Moreover, DHI inhibited CAS-3, MMP-2 and MMP-9 expression and formation of acellular capillaries in retinas that can prevent diabetes-induced apoptosis and protect retinas against diabetes-induced damage." (PMID 26061387, 2015). "However, previous studies suggest that high expression of MMP-9 results in inadequate wound healing of foot ulcers in patients with diabetes and contribute to exercise inflammation." (PMID 25884474, 2015).
diabetes (continued). "Recently, much research has focused on MMP-9 because it acts as a potent proinflammatory, proangiogenic and pro-apoptotic factor, and in diabetes, latent MMP-9 is activated in the retina and facilitates retinal capillary cell apoptosis, which is a pathological hallmark of DR development." (PMID 23671886, 2013). "Therefore, inhibitors of Raf-MEK-ERK pathway represent a unique opportunity to prevent MMP-9 induction in the retina induced by diabetes." (PMID 23671886, 2013). "Deletion of uPAR in mice preserved the BRB and blocked diabetes-induced increases in MMP9 activity." (PMID 23951261, 2013). "Diabetes/high glucose-induced increases in MMP9 activity in retinal tissues in vivo and retinal endothelial cells in vitro and alterations in composition of the perivascular extracellular matrix have been linked to retinal vascular injury and compromised barrier function." (PMID 23951261, 2013). "Evidences also suggest a total increase both in vascular and renal MMP-9 in diabetes and that endothelium may be partially responsible for this." (PMID 23209733, 2012). "So we believe that inhibiting the activity of MMP9 may be a feasible way to accelerate the healing of diabetes skin ulcers." (PMID 22577368, 2012). "In a rat model of diabetes, we investigated whether reduced HIF/VEGF/Akt/eNOS/MMP-9 signaling in the bone marrow may underlie impaired EPCs mobilization in response to AMI as compared to control (non-diabetic) rats." (PMID 23226370, 2012). "Then, the aim of this study was to investigate the possible microbiological changes and the spatial distribution and the number of immunostained cells to RAGE, TNF-alpha, IL-1beta, IL-6, RANKL and MMP-2, and MMP-9, in periodontal tissue after diabetes induction." (PMID 22611374, 2012). "Interestingly, diabetes-related alterations of the extracellular matrix and adhesion molecules were varied; Pecam, Mmp10, Lamc1, Itgb7, Mmp9, and Timp4 were up-regulated, but Col11a1, Fn1, Admts2, and Itgav were down-regulated." (PMID 21984919, 2011). "The serum MMP-9 levels were significantly higher in the patients with severe OSA and were associated with T90 or the AHI after adjusting for potential confounders such as BMI, smoking status, and comorbidities including hypertension, diabetes mellitus, COPD, and asthma." (PMID 40117070, 2025). "Statistically significant differences in lipocalin-2 and MMP-9 could be observed when comparing patients with a diabetes duration < 5 years and patients with a diabetes duration of 5–10 years (P = 0.008 for both), but not in comparison to patients with a diabetes duration > 10 years." (PMID 38932813, 2024). "However, some studies report increased MMP activity, particularly MMP-1, MMP-2, and MMP-9, with higher blood glucose levels, which could counteract any protective effect of diabetes against AD." (PMID 39105077, 2024). "When investigating FGF21, Cystatin C, lipocalin-2, and MMP-9 in this study from diagnosis of type 1 diabetes over time, Cystatin C showed most promising results with increased values from diagnosis to follow-up and inverse correlation to HbA1c and duration of diabetes." (PMID 38932813, 2024). "Additionally, the expression level of MMP-9 reduced significantly following BMP-7 treatment, which suggests BMP-7 treatment decreased both vascular and interstitial fibrosis as well as extracellular profibrotic protein MMP-9 in the diabetes-induced muscle myopathy." (PMID 36829889, 2023). "We hypothesize that MMP8 and MMP9 may play an important role in the pathogenesis of diabetic OA." (PMID 33468174, 2021). "Evidence supports the theory that hyperglycaemia associated with diabetes causes dysregulation of MMPs in primary cells from the vasculature (macrophages and endothelial cells), and that both MMP‐2 and MMP‐9 may be involved in the rupture of atherosclerotic plaques." (PMID 33855203, 2021). "However, limited evidence exists on the effect of Valsartan on MMP-9 expression in diabetes." (PMID 34082748, 2021).
diabetes (continued). "Therefore, MMP-2, MMP-9, MMP-11, MMP-13, and TIMP-4 could be important biomarkers to evaluate in diabetes and associated disorders." (PMID 33419373, 2020). "Furthermore, Parkar, Bhatt, and Addepalli hypothesized that nobiletin, due to its metalloproteinase (MMP)-2- and MMP-9-inhibitory and antioxidant potential, could ameliorate the cardiovascular dysfunction in diabetes." (PMID 32977511, 2020). "In our study, diabetes did not associate with serum MMP-9 levels." (PMID 29349668, 2018). "PAI-039 treatment increased active uPA and matrix metalloproteinase-9 (MMP-9) levels in Akita mouse tibialis anterior (TA) muscles, supporting the hypothesis that PAI-1 suppresses the proteolytic activity of uPA and MMP-9 in diabetes, thereby impairing the regenerative process." (PMID 23951058, 2013). "The proinflammatory cytokine profiles in the diabetes mellitus patients, including IL-8, were correlated with severity of the course of disease and polymorphisms of pro-inflammatory cytokine genes (CCL2, TGFB1, IL8, CCR5, and MMP9) were found to be associated with the risk of diabetic nephropathy." (PMID 24386171, 2013). "However, whether the changes in biological behaviors of fibroblasts are related to high MMP9 expression in the diabetes is still unknown." (PMID 22577368, 2012). "All the confounders selected via the Lasso method— hypertension, diabetes mellitus, COPD, and asthma—are pathophysiologically related to MMP-9." (PMID 40117070, 2025). "This study was performed to analyze the effect of PRP on traumatic ulcers with diabetes mellitus in an animal model by analyzing the expression of transforming growth factor β1 (TGF-β1) and matrix metalloprotein 9 (MMP-9)." (PMID 37172947, 2024). "High levels of MMP-2, MMP-3, MMP-8 and MMP-9 have been found in the epithelium and stroma of melted and perforated corneas after topical NSAID use and in patients with diabetes." (PMID 38528481, 2024). "PRP heals traumatic ulcers in patients with diabetes mellitus by promoting the expression of TGF-β1 and suppressing that of MMP-9." (PMID 37172947, 2024). "In Cox regression analysis, we identified diabetes, smoking, high CAVI and MMP-9 levels, and low GSM as independent predictors of MACE." (PMID 37759829, 2023). "Diabetes augments the expression of matrix metalloproteinase (MMP)-9 in the skin and its keratinocytes, and a high level of MMP-9 leads to impairments to skin wound healing, in which AGE-induced demethylation of MMP-9 promoter plays a key role." (PMID 36866277, 2023). "Regarding the post-intervention follow-up period, the presence of diabetes, smoking, high CAVI and MMP-9 levels, and low GSM independently predicted the occurrence of MACE, despite the GDMT received by all patients." (PMID 37759829, 2023). "In logistic regression analysis, CAD (OR = 1.56, p < 0.001), diabetes (OR = 1.72, p = 0.023), CAVI (OR = 1.29, p = 0.012), serum MMP-9 (OR = 1.38, p < 0.001) remained independent predictors of significant carotid atherosclerosis." (PMID 37759829, 2023). "In this study, through bioinformatics analysis, we screened seven DCRGs, including PPARG, MMP9, CTNNB1, TNF, TGFB1, PTGS2, and HIF1A, and established a DCIN to comprehensively understand the diabetes-inflammation-cancer interaction." (PMID 37033970, 2023). "Several natural products and their extracts targeting potential receptors for diabetes treatment such as dipeptidyl peptidase-IV (DPP-4) and matrix metalloproteinase-9 (MMP-9) for wound healing of DFU have been well studied and reviewed." (PMID 37894660, 2023). "In univariate analysis, age, CAD, diabetes, CAVI, serum MMP-7, MMP-9, and TIMP-1 correlated with established carotid atherosclerosis." (PMID 37759829, 2023). "In the whole study cohort, CAVI, serum MMP-9, CAD, and diabetes emerged as independent predictors of carotid atherosclerosis presence." (PMID 37759829, 2023).
diabetes (continued). "Chronic skin wounds in patients with diabetes have high levels of MMP-9 and low levels of TIMPs with resultant high MMP-9/TIMP ratios." (PMID 37266425, 2023). "Most importantly, diabetes and smoking, together with a low GSM score and high CAVI and MMP-9, independently predicted the occurrence of MACE in the post-revascularization period, which has not previously been studied." (PMID 37759829, 2023). "Matrix metalloproteinase 9 (MMP9), an endoprotease involved in inflammation-induced tissue remodeling, is hyperactivated in CVD, neurodegeneration, and diabetes." (PMID 36712965, 2022). "The secondary genes TNFAIP, MMP9, and CXCL showing interaction with PTX3 have a potential role in diabetes mellitus." (PMID 36051390, 2022). "The mean serum ACE (92.35±10.28), oxLDL (48.59±8.56), hs-CRP (5.87±1.62), MMP-9 (89.20±30.19), and MDA (1.146±0.198) levels were significantly (p-value <0.0001) higher in smokers with CHD and diabetes (group 3) when compared to group 1 and group 2." (PMID 36110446, 2022). "Diabetes patients’ recorded increased levels of OPG, RANKL, TNF-α, MMP-9, IL-18 and TOS compared to controls both pre- and post-extraction." (PMID 34829612, 2021). "In vivo, the ratio of MMP2/TIMP2 and MMP9/TIMP1 was also elevated in the skin of diabetes mice by qPCR analysis Therefore, MMP-2 and MMP-9 inhibitors were administered to the STZ-induced diabetic mice to evaluate the changes in skin collagen in vivo." (PMID 34777244, 2021). "We hypothesise that the minor allele of genetic variant rs3918242 in the promoter region of the MMP-9 gene is associated with hypertension and/or myocardial infarction, with resultant progression of dysfunctional cardiac remodelling in patients with diabetes without symptomatic heart failure." (PMID 33579197, 2021). "The bioavailability of VEGF-A is regulated by its processing by MMPs, especially MMP-9, expressed in podocytes and regulated by P2X7R upregulated in diabetes." (PMID 33635529, 2021). "Treatment with GYY substantially mitigated the elevated expression of RXRα, RXRβ and RARγ1, suggesting an RXR and RAR regulatory role by GYY to mitigate PAI-1, MMP-9, MMP-13; thus, ECM turnover in diabetic kidney." (PMID 34680110, 2021). "MMP-2 was upregulated, MMP-9 was unchanged, and MMP-28 was downregulated in consequence of diabetes development." (PMID 33923282, 2021). "Diabetes activates MMP-9 in the retina and its vasculature and MMP-9 is also activated by homocysteine." (PMID 32150828, 2020). "The data showed that compared with the control group, the expression levels of CASP3, VCAM-1 and HGF were down-regulated in patients with syphilis and diabetes, while ALB, FN1, MMP9, IL8, CTGF, STAT3 and IGF1 were up-regulated." (PMID 32342229, 2020). "In the late period of diabetes, decreased activity of MMP-2 and MMP-9 is observed with increased activity of tissue inhibitor of metalloproteinases-1 (TIMP-1)." (PMID 32403389, 2020). "The recent results advocate that due to diabetes, the overexpression of MMP-2 and MMP-9 in the retina inhibits cell proliferation and differentiation and accelerates apoptosis, a phenomenon that precedes the development of histopathology characteristic of DR." (PMID 32403389, 2020). "Generally, either cancer itself, diabetes, or both induced abnormal MMP-2 and MMP-9 overproduction, which should be further studied to address these unanswered questions." (PMID 33251135, 2020). "To investigate the influence of medication and diabetes on PR3, ANX3, MMP9, and DEFA1 levels, we segregated our subjects based on either diabetes status or statin treatment." (PMID 31935243, 2020). "Increased levels of MMP-2 and MMP-9 are observed in type 1 diabetic patients and animal models, such as STZ-induced diabetes mellitus in rats, and are associated with microvascular complications of DM." (PMID 32093214, 2020).